PLPPR3 (phospholipid phosphatase related 3)
Synonyms: PRG-2; LPPR3; PRG2; FLJ11535; LPR3
Tractability: Antibody: UniProt predicts a signal peptide or a membrane-spanning region; its Gene Ontology location is reachable by antibodies, with medium confidence. PROTAC: ubiquitination databases record sites on it; its protein half-life has been measured.
Gene: Protein-coding gene on chromosome 19 (812,487 to 822,619, reverse strand). Ensembl gene ENSG00000129951.
Subcellular location: Membrane
Subcellular location (Human Protein Atlas): Golgi apparatus; Cytosol; Nucleoplasm
Pathways (Reactome):
Signal Transduction: Lysosphingolipid and LPA receptors
Gene Ontology:
Biological process: phospholipid dephosphorylation; phospholipid metabolic process; signal transduction
Cellular component: plasma membrane; membrane
Genetic constraint (gnomAD): Loss-of-function variants: 15 observed, 22.33 expected, observed/expected ratio (o/e) 0.67, 90% interval 0.45 to 1.03. The synonymous counts are far from expectation, so gnomAD's model fits this gene poorly and the ratio says little. Missense variants: 1,284 observed, 845.39 expected, observed/expected ratio (o/e) 1.52, 90% interval 1.45 to 1.59. Synonymous variants: 671 observed, 418.2 expected, observed/expected ratio (o/e) 1.6, 90% interval 1.5 to 1.71.
Homologues: Orthologues: macaque PLPPR3 (99% identical), chimpanzee PLPPR3 (98% identical), pig PLPPR3 (93% identical), dog PLPPR3 (90% identical), mouse Plppr3 (89% identical), rat Plppr3 (88% identical), guinea pig PLPPR3 (87% identical), tropical clawed frog plppr3 (67% identical), zebrafish plppr3a (59% identical), zebrafish plppr3b (57% identical), Drosophila melanogaster CG11438 (11% identical), Caenorhabditis elegans plpp-1.1 (10% identical), and 7 more. Paralogues in human: PLPPR4 (47% identical), PLPPR2 (17% identical), PLPPR1 (17% identical), PLPPR5 (16% identical), PLPP1 (11% identical), PLPP3 (11% identical), PLPP2 (10% identical), PLPP5 (8% identical), PLPP4 (8% identical).
Diseases named in the same sentence as PLPPR3 in open-access papers:
PLPPR3 is named in the same sentence as 8 diseases in open-access papers, as found by Europe PMC text mining. Sharing a sentence is not in itself a finding about the gene and the disease. The quoted sentences say what the papers report.
glioma (1 paper, 2024). A benign or malignant brain and spinal cord tumor that arises from glial cells (astrocytes, oligodendrocytes, ependymal cells). "Moreover, DUSP11, LPIN3, MTMR11, HDDC2, and PLPPR3 have not been queried for glioma-related studies." (PMID 39830513, 2024).
lung carcinoma (1 paper, 2024). "Finally, EIF4G1 displays diverse interactions in LUSC, linking with LUAD-related ZFHX4, COL6A6, and unusual PLPPR3 connections to lung cancer genes." (PMID 38389572, 2024).
neuroblastoma (1 paper, 2022). Neuroblastoma (NB) is the most common solid, extracranial childhood tumor. "PLPPR1 overexpression in neuroblastoma cells increases the number and length of neurites, while PLPPR3 expression in stem-cell derived motor neurons led to a PI3K-dependent formation of multiple axons per cell." (PMID 36187351, 2022). "Furthermore, super resolution microscopy of co-overexpressed PLPPR1 and PLPPR5 or PLPPR3 showed both puncta formation at the plasma membrane in neuroblastoma cell lines." (PMID 36187351, 2022).
PLPPR3 also shares sentences with these, for which no sentence is quoted: acrodysostosis (2 papers); cancer (1); Hypocalcemia (1); progressive osseous heteroplasia (1); pseudopseudohypoparathyroidism (1).